PMCH (pro-melanin concentrating hormone)
Description:
[Melanin-concentrating hormone]: Neuropeptide ligand for the G protein-coupled receptor MCHR1 and MCHR2 that can activate both G(i/o)- and G(q/11)-dependent signaling pathways. Acts as a neuromodulator in the central nervous system, promoting feeding, positive energy balance (orexigenic) and sleep. Inhibits stimulated ACTH release (lowering plasma glucocorticoids), consistent with a role in down-regulating hypothalamic-pituitary-adrenal (HPA) axis activity. Functionally antagonizes melanotropin alpha (alpha-MSH), opposing its inhibitory effect on food intake and exploratory behaviors and its stimulatory effect on the HPA axis. Antagonizes NEI-induced behavioral effects (By similarity). May also participate in spermatocyte differentiation (By similarity). [Neuropeptide-glutamic acid-isoleucine]: Neuropeptide that modulates stress-related neuroendocrine responses and behaviors. Stimulates ACTH secretion, functionally counteracting the ACTH-suppressing action of MCH; the underlying mechanism is not fully characterized. Reduces dopamine and DOPAC release in the ventromedial nucleus. Influences differentiation of neuronal processes and affects neurofilament protein content in vitro.
Synonyms: MCH; ppMCH
Tractability: Antibody: its Gene Ontology location is reachable by antibodies, with high confidence; UniProt places it where antibodies can reach, with medium confidence; UniProt predicts a signal peptide or a membrane-spanning region.
Safety:
Unwanted effects reported when the protein is acted on. In parentheses: how it was acted on, where the effect was seen, and who reports it.
obesity (source: ClinPGx)
Gene: Protein-coding gene on chromosome 12 (102,196,459 to 102,197,833, reverse strand). Ensembl gene ENSG00000183395.
Subcellular location: Secreted (Melanin-concentrating hormone); Secreted (Neuropeptide-glutamic acid-isoleucine)
Pathways (Reactome):
Signal Transduction: G alpha (i) signalling events; G alpha (q) signalling events; Peptide ligand-binding receptors
Gene Ontology:
Molecular function: type 1 melanin-concentrating hormone receptor binding; melanin-concentrating hormone activity
Biological process: feeding behavior; negative regulation of synaptic transmission, dopaminergic; chemical synaptic transmission; regulation of feeding behavior; signal transduction
Cellular component: extracellular region; nucleus; synapse
Genetic constraint (gnomAD): Loss-of-function variants: 5 observed, 10.68 expected, observed/expected ratio (o/e) 0.47, 90% interval 0.24 to 0.99. The upper end of that interval is the gene's LOEUF score, 0.99, which puts it in group 4 of 6, group 1 being the genes least tolerant of losing a copy. Missense variants: 128 observed, 148.82 expected, observed/expected ratio (o/e) 0.86, 90% interval 0.74 to 1. Synonymous variants: 58 observed, 51.53 expected, observed/expected ratio (o/e) 1.13, 90% interval 0.91 to 1.4.
Homologues: Orthologues: chimpanzee PMCH (98% identical), macaque PMCH (98% identical), dog PMCH (93% identical), rabbit PMCH (91% identical), pig PMCH (90% identical), mouse Pmch (87% identical), guinea pig PMCH (84% identical), rat Pmch (82% identical), tropical clawed frog pmch (54% identical), zebrafish pmch (25% identical), zebrafish pmchl (19% identical).
Diseases named in the same sentence as PMCH in open-access papers:
PMCH is named in the same sentence as 114 diseases in open-access papers, as found by Europe PMC text mining. Sharing a sentence is not in itself a finding about the gene and the disease. The quoted sentences say what the papers report.
Obesity (56 papers, 2007 to 2025). Accumulation of substantial excess body fat. "Overexpression of MCH in mice leads to obesity and insulin resistance, and in contrast, pMCH−/− and MCH-neuron-ablated mice are lean with improved insulin sensitivity." (PMID 25084113, 2014). "Moreover, the first genome scan targeting obesity as a side effect of antipsychotics has observed an implication of the pro-melanin-concentrating hormone (PMCH), the precursor of MCH." (PMID 26461262, 2015). "Pro-Melanin-concentrating hormone (Pro-MCH) is a prohormone of melanin-concentrating hormone (MCH), tightly connected to obesity and increased food intake in animals." (PMID 33348610, 2020).
Insulin resistance (11 papers, 2007 to 2025). Increased resistance towards insulin, that is, diminished effectiveness of insulin in reducing blood glucose levels. "After omentectomy, plasma leptin, insulin, NPY, AGRP, and PMCH levels decreased, which may result a decrease in leptin and insulin resistance." (PMID 29367725, 2018).
migraine (4 papers, 2014 to 2022). "Pro-melanin concentrating hormone (PMCH) has been associated with the influence of eating and glucose on migraines." (PMID 35453627, 2022).
schizophrenia (4 papers, 2011 to 2024). A major psychotic disorder characterized by abnormalities in the perception or expression of reality. "PMCH is linked to motivated behavior, social impairment, and the progression of psychiatric disorders, such as schizophrenia." (PMID 38473814, 2024).
lymph node metastasis (1 paper, 2022). "This study constructed a prognostic model of genes related to lymph node metastasis in COAD and found that PMCH, CD1B, NAT1, NKAIN4, and LRP2 have prognostic, predictive values." (PMID 36727052, 2022).
osteoporosis (1 paper, 2024). A condition of reduced bone mass, with decreased cortical thickness and a decrease in the number and size of the trabeculae of cancellous bone (but normal chemical composition), resulting in increased fracture incidence. "In osteoporosis model, we chemogenetically activated MCH neurons in LH when age induced osteoporosis was seen in pMCH‐Cre mice in 18 months old." (PMID 39320347, 2024).
renal clear cell carcinoma (1 paper, 2022). "In renal clear cell carcinoma, the low expression of PMCH is significantly related to higher tumor stages, more chances of metastasis, and poor prognosis." (PMID 36727052, 2022).
tumor (7 papers, 2012 to 2022). "Taking these previous findings into consideration, we decided not to rule out the CR pathway as a possible contributor to PMCH tumor formation and continued to incorporate these genes into subsequent analyses." (PMID 27391266, 2016).
PMCH also shares sentences with these, for which no sentence is quoted: depression (26 papers); Anxiety (21); Cataplexy (11); asthma (8); cancer (8); infection (8); narcolepsy (7); psychiatric disorder (7); Alzheimer disease (6); melanoma (6); Parkinson disease (5); sleep disorder (5); Hepatic steatosis (4); metabolic disease (4); vitiligo (4); airway hyperresponsiveness (3); amyotrophic lateral sclerosis (3); anxiety disorder (3); cognitive deficits (3); colitis (3); Glucose intolerance (3); hypersomnia (3); inflammatory bowel disease (3); mood disorder (3); Rett syndrome (3); amyloidosis (2); Anorexia (2); colon adenocarcinoma (2); colon carcinoma (2); diabetes (2).
A further 76 diseases each share a sentence with PMCH in 2 papers or fewer.